PCDHGA6 (protocadherin gamma subfamily A, 6)
Description:
Potential calcium-dependent cell-adhesion protein. May be involved in the establishment and maintenance of specific neuronal connections in the brain.
Synonyms: PCDH-gamma-A6
Tractability: Antibody: UniProt places it where antibodies can reach, with medium confidence; UniProt predicts a signal peptide or a membrane-spanning region; its Gene Ontology location is reachable by antibodies, with medium confidence; the Human Protein Atlas places it where antibodies can reach.
Gene: Protein-coding gene on chromosome 5 (141,373,891 to 141,512,975, forward strand). Ensembl gene ENSG00000253731.
Subcellular location: Cell membrane
Subcellular location (Human Protein Atlas): Nucleoplasm; Plasma membrane; Cytosol; Vesicles
Gene Ontology:
Molecular function: cell adhesion molecule binding; calcium ion binding
Biological process: cell adhesion; homophilic cell-cell adhesion
Cellular component: plasma membrane; membrane
Genetic constraint (gnomAD): Loss-of-function variants: 41 observed, 63.8 expected, observed/expected ratio (o/e) 0.64, 90% interval 0.5 to 0.83. The upper end of that interval is the gene's LOEUF score, 0.83, which puts it in group 3 of 6, group 1 being the genes least tolerant of losing a copy. Missense variants: 1,312 observed, 1,263.9 expected, observed/expected ratio (o/e) 1.04, 90% interval 0.99 to 1.09. Synonymous variants: 594 observed, 552.44 expected, observed/expected ratio (o/e) 1.08, 90% interval 1 to 1.15.
Homologues: Orthologues: guinea pig PCDHGA6 (82% identical), mouse Pcdhga6 (80% identical), pig PCDHGA6 (70% identical). Paralogues in human: PCDHGA7 (77% identical), PCDHGA3 (76% identical), PCDHGA4 (76% identical), PCDHGA10 (76% identical), PCDHGA5 (76% identical), PCDHGA2 (75% identical), PCDHGA1 (75% identical), PCDHGA8 (75% identical), PCDHGA12 (74% identical), PCDHGA11 (74% identical), PCDHGA9 (73% identical), PCDHGB5 (53% identical), and 49 more.
Diseases named in the same sentence as PCDHGA6 in open-access papers:
PCDHGA6 is named in the same sentence as 4 diseases in open-access papers, as found by Europe PMC text mining. Sharing a sentence is not in itself a finding about the gene and the disease. The quoted sentences say what the papers report.
cervical cancer (1 paper, 2022). A primary or metastatic malignant neoplasm involving the cervix. "Most of the PCDHG family (e.g. PCDHGB3 and PCDHGA6) are calcium-dependent cell-adhesion proteins, significantly mutated in SC1 patients and previously reported as diagnostic markers for cervical cancer." (PMID 35439935, 2022).
colorectal cancer (1 paper, 2022). A primary or metastatic malignant neoplasm that affects the colon or rectum. "A functional role for the hypermethylation and gene silencing of PCDHαβγ family genes (PCDHAC2, PCDHB7, PCDHB15, PCDHGA1 and PCDHGA6) was also identified recently in colorectal cancer influencing the WNT/B-catenin pathway implicated in proliferation, survival and migration." (PMID 36443814, 2022).
infection (1 paper, 2025). The state of being infected such as from the introduction of a foreign agent such as serum, vaccine, antigenic substance or organism. "PCDHGA6 was upregulated in mice infected with Plasmodium berghei, and a gene that activates PCDHGA6 and PCDH10 was downregulated in experimentally infected 'amakihi that succumbed to infection." (PMID 40909016, 2025). "For instance, among the genes upregulated in infected wild‐caught birds reported here, RAB20 was also upregulated in 'amakihi surviving experimental infection, and three upregulated genes (COG5, BOD1, and PCDH10 which activates PCDHGA6) were downregulated in 'amakihi that perished." (PMID 40909016, 2025).
PCDHGA6 also shares sentences with these, for which no sentence is quoted: malaria (1 paper).